CXCL8 (C-X-C motif chemokine ligand 8)
Diseases named in the same sentence as CXCL8 in open-access papers (continued):
Sharing a sentence is not in itself a finding about the gene and the disease.
microcephaly (9 papers, 2015 to 2024). A congenital or acquired developmental disorder in which the circumference of the head is smaller than normal for the person's age and sex. "This apporach revealed significantly different frequencies in the rs4073 SNP in the CXCL8 gene, and the rs179008 in the TRL7 gene between the groups, associating these SNPs with the severity of microcephaly." (PMID 36859461, 2023). "In this study, TREM1 rs2234246 and IL4 rs224325 in mothers infected with ZIKV during pregnancy was found to be associated with the occurrence of CZS microcephaly and the SNP CXCL10 rs4508917 and CXCL8 rs4073 in their children with presence of CZS microcephaly." (PMID 36859461, 2023). "For instance, higher levels of CXCL8/IL8 have been found in the cerebrospinal fluid of neonates without CZS who were born to mothers infected with ZIKV during pregnancy than in those born with CZS-related microcephaly." (PMID 38839691, 2024). "Furthermore, the CXCL8 rs4073 and TRL7 rs179008 SNPs were associated with the severity of microcephaly in children with CZS." (PMID 36859461, 2023). "Furthermore, the T allele at CXCL8 rs4073 and TRL7 rs179008 SNPs were associated with the severity of microcephaly in children with CZS." (PMID 36859461, 2023). "Stratifying the case group of children (C-MICRO) by the severity of microcephaly at birth, in children with severe microcephaly (CSM) and children with microcephaly (CM), the T allele in SNP rs4073 at CXCL8 gene and the T allele in SNP rs179008 at TRL7 was associated with severe microcephaly." (PMID 36859461, 2023). "The microcephaly group exhibited significantly decreased CCL2 and CXCL8 levels in serum, quantified by CBA assay." (PMID 37766239, 2023). "Furthermore, higher levels of CXCL-8 in cerebrospinal fluid were found in neonates without CZS who were born from mothers infected with ZIKV during pregnancy, when compared to those born with microcephaly by CZS, suggesting an important role of this chemokine in protection against CZS26." (PMID 36859461, 2023).
neuroendocrine tumor (9 papers, 2013 to 2024). "CXCR2 is overexpressed predominantly in neuroendocrine tumor (NE) cells, which produce CXCL8; whereas, CXCR1 expression appears to be restricted to non-NE tumor cells." (PMID 39766038, 2024).
sickle cell disease (9 papers, 2009 to 2025). Sickle cell anemias are chronic hemolytic diseases that may induce three types of acute accidents: severe anemia, severe bacterial infections, and ischemic vasoocclusive accidents (VOA) caused by sickle-shaped red blood cells obstructing small blood vessels and capillaries. "High levels of IL-6 and CXCL8 are also associated with poorer clinical outcomes in sickle cell anemia." (PMID 36232655, 2022). "It is well-known that hydroxycarbamide (hydroxyurea), a cytoredutor drug indicated for MPN treatment, is capable of lowering serum inflammatory markers such as TNF-α, IL-6, CXCL8, and IL-1β in sickle cell disease patients." (PMID 34084749, 2021).
syphilis (9 papers, 2016 to 2026). A contagious bacterial infection caused by the spirochete Treponema pallidum. "Third, in patients co-infected with HIV and syphilis, the presence of CXCL13, CXCL10 and CXCL8 in CSF could be associated with syphilis, HIV or both." (PMID 27650493, 2016). "In addition, patients with NS had a higher CXCL8 level in their CSF compared to patients with syphilis and other CNS infections." (PMID 41221293, 2025). "Even though the levels of CXCL8 in the CSF of other CNS infection patients were greater than those of syphilis patients, the difference was not significant." (PMID 41221293, 2025).
acute GVHD (8 papers, 2013 to 2024). "Notably, reduced levels of CXCL8 in plasma on day +7 were associated with grade II–IV acute GVHD." (PMID 39840040, 2024). "One reason for this particular importance of CXCL8 could be that it is important both in inflammation and as a proangiogenic chemokine that may be involved in the neovascularization known to take place in acute GVHD." (PMID 23430540, 2013). "The four markers, CXCL8, IL2R-α, TNFR1 and HGF, identified above showed increased levels in acute GVHD, and increased levels of these markers have also been identified in other clinical studies." (PMID 23430540, 2013).
chronic pancreatitis (8 papers, 2009 to 2025). A chronic inflammatory process causing damage and fibrosis of the pancreatic parenchyma. "We found elevated levels of PGE2 and CXCL8 in subjects with PDAC, and chronic pancreatitis." (PMID 20214814, 2010).
Ebola virus disease (8 papers, 2011 to 2025). "Indeed, IL6 and CXCL8 are elevated 100- to 1000-fold in Ebola patients, and can reach extremely high bloodborne levels (>1 ng/mL) in vivo." (PMID 41279810, 2025). "Taken together, Ebola seemingly triggers “immunological misfiring”111 in human ECs by elevating inflammatory cytokines (e.g., IL6 and CXCL8), in the virtual absence of interferon and antiviral ISGs." (PMID 41279810, 2025).
Hydrocephalus (8 papers, 2021 to 2024). Hydrocephalus is an active distension of the ventricular system of the brain resulting from inadequate passage of CSF from its point of production within the cerebral ventricles to its point of absorption into the systemic circulation. "First of all, the explanation for the significantly higher level of CXCL8 / IL8 in the control group is the immune response to damage of the ependymal lining, which is caused by an increase in intracranial pressure as a consequence of hydrocephalus." (PMID 39121090, 2024).
lower respiratory tract infection (8 papers, 2014 to 2022). "Th17 lineage cytokines (IL-17A, IL-17F, and IL-22) and chemokines (CXCL1, CXCL2, CXCL5, and CXCL8) are known to control chronic lung infection caused by mycobacteria." (PMID 33520738, 2020).
Miscarriage (8 papers, 2014 to 2025). A pregnancy that ends at a stage in which the fetus is incapable of surviving on its own, defined as the spontaneous loss of a fetus before the 22th week of pregnancy. "First‐trimester miscarriage is associated with reduced IL‐6 and CXCL8 production, and lower IL‐6 transcription is evident in the uterine endometrium of women with recurrent miscarriages, compared with fertile women." (PMID 34408876, 2021). "In addition IL1 β, IL-6, IL-10 and CXCL8 (IL-8) have previously been examined in maternal circulation in association with miscarriage." (PMID 24699265, 2014). "In conclusion, we have found plasma concentrations of the cytokines IL-1β, IL-6 and IL-10, and the chemokines, CXCL8, CCL2, CCL5, CCL7, CX3CL1 cannot predict subsequent miscarriage." (PMID 24699265, 2014).
Myalgia (8 papers, 2017 to 2025). "Although no strong or statistically significant association was found between SNPs in proinflammatory cytokine genes and specific TMD-related conditions such as arthralgia and myalgia, there was a very weak association between a specific genotype in the CXCL8 gene and arthralgia." (PMID 39201416, 2024). "CRP was significantly higher in patients with these symptoms, while chemokines CCL2 (MCP-1), CCL3 (MIP-1α) and CXCL8 (IL-8) were higher in patients with rigors and myalgia." (PMID 41027884, 2025).
oropharyngeal squamous cell carcinoma (8 papers, 2015 to 2025). "In HPV-negative Oropharyngeal Squamous Cell Carcinoma (OPSCC), it has been demonstrated that the IL-1/IL-1R axis produces chemokine CXCL8, leading to poor prognosis in OPSCC." (PMID 39461030, 2024).
peritonitis (8 papers, 2014 to 2025). Inflammation of the peritoneum (tissue that lines the abdominal wall and covers most of the organs in the abdomen). "In this study, the effluent from three patients with peritonitis induced CCL2 and CXCL8 secretion by mesothelial cells while effluent from stable patients showed only background activity." (PMID 27527598, 2016). "In this study, the effluent of PD patients presenting with acute peritonitis, before commencing antibiotic treatment, contained increased levels of total cells and of chemokines like the neutrophil-attracting molecule CXCL8 (IL-8), compared with effluent from stable noninfected PD patients." (PMID 27527598, 2016).
rheumatic diseases (8 papers, 2006 to 2024). "Synovial fluids from patients (n = 126) with rheumatic diseases including RA, AS, PsA and CA were analysed for their CXCL8 and CXCL10 content by specific ELISAs." (PMID 16846531, 2006).
ventilator-associated pneumonia (8 papers, 2005 to 2025). Serious INFLAMMATION of the LUNG in patients who required the use of PULMONARY VENTILATOR. "We also show nitrated CXCL8 in bronchoalveolar lavage (BAL) samples from patients with suspected ventilator-associated pneumonia (VAP)." (PMID 36622452, 2023).
visceral leishmaniasis (8 papers, 2012 to 2025). A severe form of leishmaniasis characterized by irregular bouts of fever, substantial weight loss, swelling of the spleen and liver, and anemia (which may be serious). "From the results of DisGeNET, the hub genes IL10, IL6, CXCL8, CSF2, IFNG, IL1B, and TNF were causing Visceral Leishmaniasis; IL10, IL4, CXCL8, IFNG, IL1B and TNF found to cause Cutaneous Leishmaniasis and Urban Cutaneous Leishmaniasis." (PMID 36989283, 2023). "Validation of our DP cohort results revealed that CXCL10, but not CCL2, CCL5 or CXCL8 transcripts, were significantly upregulated by Leishmania infantum infection with or without clinically definite visceral leishmaniasis." (PMID 37601355, 2023).
Anorexia (7 papers, 2014 to 2024). Lack of desire to eat (loss of appetite). "A number of cytokines have been previously linked to anorexia, including IL-6, TNF-α, CXCL8, IL-1β, IL-18, IL-2, and IFN-γ." (PMID 32071269, 2020).
bacterial pneumonia (7 papers, 2018 to 2025). Acute infection of the lung parenchyma caused by bacteria (e.g., Streptococcus pneumoniae, Haemophilus influenzae, Chlamydia pneumoniae, Mycoplasma pneumoniae, and Legionella pneumophila). "Severe bacterial pneumonia was marked by an inflammatory cytokine storm resulting from systemic upregulation of S100A8/A9 and CXCL8, primarily due to specific macrophage and neutrophil subsets." (PMID 39757231, 2025).
Bovine mastitis (7 papers, 2012 to 2025). INFLAMMATION of the UDDER in cows. "Our data suggest that genes TLR4, NOD2, CXCL8, and OAS2 are key components involved in the host immune response to bovine mastitis and that the lncRNAs MSTRG25101.2, MSTRG.56327.1, and MSTRG.18968.1 adjacent to the SCC QTL and SCS QTL may potentially regulate expression of these candidate genes." (PMID 36204322, 2022).
cardiomyopathy (7 papers, 2018 to 2025). A disease of the heart muscle or myocardium proper. "Interestingly, CXCL10 and CXCL8 significantly increased in sera of diabetic subjects at the onset of cardiomyopathy and are targeted by sildenafil." (PMID 39355618, 2024).
cholestasis (7 papers, 2011 to 2024). Impairment of the bile flow caused by obstruction within the liver, or outside the liver in the bile duct system. "CXCL8, NOS2, and IL-6 reportedly play a role in inflammation, hyperalgesia, cholestasis, and neoplastic cell transformation." (PMID 35720847, 2022).
corneal infection (7 papers, 2014 to 2024). A viral or bacterial infectious process affecting the cornea. "CXCL8 (encodes the IL-8 protein) had the most significant upregulation among the differentially expressed genes (DEGs) in the cornea of patients with corneal infection and was upregulated in the conjunctiva." (PMID 38694515, 2024).
Dengue hemorrhagic fever (7 papers, 2017 to 2025). A serious condition caused by Dengue virus infection. "Patients with dengue hemorrhagic fever (DHF) had significantly higher NS1,CXCL-8, and CXCL-10 serum levels thanthose with classic dengue fever (DF)." (PMID 39082520, 2024).
endometrial adenocarcinoma (7 papers, 2009 to 2022). "Another chemokine ligand of the CXCR2 receptor, CXCL8, has also been implicated in tumourigenesis by enhancing melanoma cell proliferation, alveolar epithelial neoplasia and breast cancer development, however its expression and role in endometrial adenocarcinoma is unclear." (PMID 19819266, 2009). "CXCL8, a chemokine ligand of the CXCR2 receptor, were implicated in tumorigenesis by enhancing endometrial adenocarcinoma cell and melanoma cell proliferation and alveolar epithelial neoplasia and breast cancer development." (PMID 35717152, 2022). "Using a chemokine protein array, we identified the inflammatory chemokine CXCL8 as a target for PGF2α-FP receptor signaling in endometrial adenocarcinoma cells." (PMID 19819266, 2009). "Using an adenovirus to overexpress RCAN1-4, we found that RCAN1-4 is a negative regulator of CXCL8 expression in endometrial adenocarcinoma cells." (PMID 19819266, 2009). "In the present study we identified another CXCR2 ligand, CXCL8 as a target for PGF2α-FP receptor signalling which enhances epithelial cell proliferation in endometrial adenocarcinoma cells in vitro and in nude mice in vivo." (PMID 19819266, 2009). "We next explored the expression of CXCL8 in endometrial adenocarcinoma and normal endometrial tissues and its potential regulation by PGF2α via the FP receptor." (PMID 19819266, 2009). "We subsequently investigated the regulation of CXCL8 via the F-prostanoid receptor in endometrial adenocarcinoma cells and the potential role of CXCL8 in endometrial adenocarcinomas." (PMID 19819266, 2009). "Here we identified CXCL8 as a target for PGF2α-FP receptor signaling in endometrial adenocarcinoma cells." (PMID 19819266, 2009). "We found that PGF2α-FP receptor interaction induces CXCL8 expression in endometrial adenocarcinoma cells via the protein kinase C–calcium–calcineurin–NFAT signaling pathway." (PMID 19819266, 2009). "In addition, RCAN1-4 inhibits epithelial cell proliferation in endometrial adenocarcinoma via a negative regulation of C-X-C motif chemokine ligand 8 (CXCL8)." (PMID 29416595, 2018). "Using an in vitro model system, endometrial adenocarcinoma explants and a nude mouse xenograft model, we elucidated the molecular mechanisms mediating PGF2α-FP receptor signaling to CXCL8 in endometrial adenocarcinoma cells its potential role in endometrial tumourigenesis." (PMID 19819266, 2009). "To determine whether PGF2α-FP receptor signaling regulates CXCL8 in endometrial adenocarcinomas, we determined the expression pattern and localization of CXCL8 in endometrial adenocarcinoma tissue." (PMID 19819266, 2009). "PGF2α stimulation of endometrial adenocarcinoma explants resulted in a significant increase in the expression of CXCL8 mRNA and secretion of CXCL8 protein, which was inhibited by co-treatment of tissue explants with the specific FP receptor antagonist AL8810 (P < 0.001)." (PMID 19819266, 2009). "In addition, CXCL1 and CXCL8 are chemokines that are elevated in endometrial adenocarcinoma." (PMID 30813939, 2019). "Moreover we have shown that CXCL8 expression in endometrial adenocarcinoma explants is negatively regulated by RCAN1-4 since infection of endometrial adenocarcinoma explants with RCAN1-4 adenovirus abolished the PGF2α-FP receptor-mediated induction of CXCL8." (PMID 19819266, 2009). "Furthermore, we confirmed that RCAN1-4 is a potent negative regulator of CXCL8 in vitro and ex vivo in endometrial adenocarcinomas explants and that the regulation of transcriptional activation of CXCL8 by PGF2α occurs via the co-operativity between AP1 and NFAT DNA binding elements." (PMID 19819266, 2009). "Taken together, our data show that PGF2α-FP receptor activation in endometrial adenocarcinoma cells promotes the activation of RCAN1-4 and CXCL8 via the Gq-PLC-PKC–calcium–calcineurin–NFAT." (PMID 19819266, 2009).
endometrial adenocarcinoma (continued). "CXCL8 mRNA expression was significantly up-regulated in endometrial adenocarcinoma irrespective of grade or stage of cancer compared with normal endometrium (P < 0.001)." (PMID 19819266, 2009). "CXCL8 immunoreactivity in endometrial adenocarcinomas was observed in the glandular epithelium (G; as indicated by the brown staining) with some diffuse stromal (S), staining irrespective of grade/stage of endometrial adenocarcinoma." (PMID 19819266, 2009). "Furthermore, infection of endometrial adenocarcinoma explants (P < 0.001) using RCAN1-4 adenovirus significantly reduced the PGF2α-FP receptor induction of CXCL8 mRNA expression compared to tissue infected with the scrambled control virus similar to our in vitro data using Ishikawa FPS cells." (PMID 19819266, 2009).
hip fracture (7 papers, 2010 to 2024). Traumatic or pathological injury to the hip in which the continuity of either the femoral head, femoral neck, intertrochanteric or subtrochanteric regions is broken. "Previous studies have examined prognostic biomarkers in hip fracture patients, such as low albumin levels, lymphocyte counts, and chemotactic cytokine CXCL-8." (PMID 39769198, 2024).
leishmaniasis (7 papers, 2013 to 2024). Infectious disease that is transmitted through the bite of hematophagous female phlebotomine sand flies. "In particular, the results propose that G0S2 and CXCL8 can be potential biomarkers and therapeutic targets for leishmaniasis." (PMID 38190401, 2024).
neovascular glaucoma (7 papers, 2018 to 2024). "Moreover, elevated levels of the pro-inflammatory cytokine CXCL8 were detected in the AH of POAG, XFG, and neovascular glaucoma (NVG) subjects and were also associated with an elevated preoperative IOP or visual field defects in the eyes of patients." (PMID 39458974, 2024).
non-alcoholic fatty liver disease (7 papers, 2017 to 2024). "Moreover, a recent systematic review and meta-analysis suggested that the chemokines, CCL3, CCL4, CCL5, CCL20, CXCL8 and CXCL11, are implicated in the pathogenesis of non-alcoholic fatty liver disease, post-traumatic stress disorder, and also different types of cancers." (PMID 35242125, 2021). "Moreover, a recent systematic review and meta-analysis suggested that chemokines, CCL3, CCL4, CCL5, CCL20, CXCL8 and CXCL11, are implicated in the pathogenesis of non-alcoholic fatty liver disease, post-traumatic stress disorder, and also different types of cancers." (PMID 34054797, 2021).
polycystic ovary syndrome (7 papers, 2021 to 2025). A disorder that manifests as multiple cysts on the ovaries. "Coptis chinensis, an important medicinal plant in the Ranunculaceae family, has been found to reverse the pathological damage of ovarian tissue in polycystic ovary syndrome and regulate the mRNA and protein expression levels of MAPK1, CXCL8, IL-6 and IL-1β." (PMID 40842497, 2025).
respiratory distress syndrome (7 papers, 2013 to 2022). "Tracheal aspirate levels of pro-inflammatory cytokines such as IL-6, IL-1β, TNF-α, and chemokines CCL2, CCL7, CCL8, and IL-8 (CXCL8) are higher in premature infants with respiratory distress syndrome who develop BPD." (PMID 33117383, 2020).
skin infection (7 papers, 2011 to 2024). An inflammatory process affecting the skin, caused by bacteria, viruses, parasites, or fungi. "Proinflammatory cytokines and chemokines, such as IL-1α, IL-6, TNFα, and CXCL8, secreted by various cell types play a fundamental role in attracting neutrophils and T cells to the place of skin infection." (PMID 21619700, 2011). "Neutrophils play an essential role in targeting and eliminating S. aureus during a skin infection, while keratinocytes are able to secrete CXCL1 and CXCL8, which are the primary chemokines responsible for neutrophil recruitment and stimulation of neutrophil degranulation." (PMID 35804301, 2022).